METTL3 (methyltransferase 3, N6-adenosine-methyltransferase complex catalytic subunit)
Diseases named in the same sentence as METTL3 in open-access papers (continued):
Sharing a sentence is not in itself a finding about the gene and the disease.
tumor (continued). "In the tumor cells, METTL3 expression was mainly detected in the nucleus, GLUT1 and HK2 were mainly detected in the cytoplasm, but GLUT1 was also detected in the cell membrane." (PMID 32626532, 2020). "The expression of METTL3 in tumour cells was positively correlated with that in tumour-infiltrating immune cells (R = 0.264, P < 0.001)." (PMID 33059689, 2020). "Here, we demonstrated that disturbances in the balance of m6A modification mediated by the METTL3/YTDHF2 axis played a crucial role in tumour cell proliferation and migration thus influencing the tumorigenesis of BCa." (PMID 32126149, 2020). "To test the tumour metastasis‐promoting effect of METTL3 in vivo, we established a mouse model of experimental metastases by caudal vein injection of 2 × 106 UM‐UC‐3 cells infected with lentiviruses." (PMID 32126149, 2020). "Some studies have shown that METTL3 expression can promote tumour cell proliferation, leading to poor patient prognosis." (PMID 33059689, 2020). "Mouse PET-CT data showed that knockout of METTL3 significantly reduced glucose uptake in xenograft mouse tumor model." (PMID 32245489, 2020). "Many studies have used METTL3 as a tumor biomarker, but the specificity and sensitivity of METTL3 in different types of gastrointestinal cancer need further study." (PMID 32429972, 2020). "In their studies, the tumour suppressor SOCS2 was identified to be the direct downstream target of METTL3." (PMID 33090698, 2020). "With in vivo models, everolimus was effective in reducing tumor volumes in both METTL3-overexpressing or control tumors." (PMID 33037176, 2020). "The m6A modification catalysed by METTL3 is recognized by YTHDF2 to mediate the mRNA decay of tumour suppressors SETD7 and KLF4, which consequently induces the BCa progression." (PMID 32126149, 2020). "In oral squamous cell carcinoma (OSCC), METTL3 can facilitate tumor growth and metastasis through making an increment in m6A modification and expression of c-Myc transcript." (PMID 33015074, 2020). "Our data showed that when the tumor volume was comparable, the expression of ERRγ and Mettl3 was increased in HepG2/ADR groups as compared to that in parental cells." (PMID 32206097, 2020). "We found that CD33+CD11b+HLA-DR− MDSCs and tumour-derived MDSCs were decreased when METTL3 was knocked down in CD33+ cells or HeLa cells." (PMID 33059689, 2020). "This study provided the first proof-of-concept model to demonstrate METTL3-mediated m6A hypermethylation as a new mechanism for epigenetic silencing of tumor suppressor gene expression in human cancers." (PMID 32111216, 2020). "Mechanistically, METTL3 regulates the m6A modification and thereby the expression of AF4/FMR2 family member 4 (AFF4), knockdown of which phenocopies the METTL3 ablation and diminishes the tumor-initiating capability of BCSCs in vivo." (PMID 32676121, 2020). "Meanwhile, METTL3 expression in lymph node metastatic and distant metastatic tissues is significantly higher than that of primary tumor tissues." (PMID 32175271, 2020). "At last, we observed that downregulation of METTL3 synergizes with the glycolysis inhibitor 2‐deoxyglucose (2‐DG) to inhibit tumor growth in vitro." (PMID 32068977, 2020). "Knockdown of METTL3 abolished the tumor suppressive effects of sorafenib in the liver tumor microenvironment compared to the control group." (PMID 32368828, 2020). "Collectively, our work reveals a critical function for METTL3‐mediated m6A modification in the hypoxic tumor microenvironment and identifies FOXO3 as an important target of m6A modification in the resistance of HCC to sorafenib therapy." (PMID 32368828, 2020). "Consistent with the increase in the MDSC population in CC patients, the level of METTL3 was increased in the peripheral and tumour-infiltrating immune cells compared with the corresponding controls." (PMID 33059689, 2020).
tumor (continued). "The accumulated expression of SETD7 and KLF4 upon METTL3 depletion was also discovered in UM‐UC‐3 derived xenograft tumours obtained from nude mice." (PMID 32126149, 2020). "The immunostaining of METTL3 was mainly found in the nuclear METTL3 were expressed in both HCC tumor cells and normal liver cells, 91 (91.0%) cases showed higher METTL3 staining in tumors areas than that in normal liver tissues." (PMID 32068977, 2020). "The levels of METTL3 and CD33+ MDSCs in tumour tissues were notably associated with reduced DFS or OS." (PMID 33059689, 2020). "METTL3 was located in the nuclei of tumour cells and tumour-infiltrating immune cells, while CD33+ cells were scattered mainly in the tumour stroma; isotype IgG was used as a control." (PMID 33059689, 2020). "To comprehensively understand the function of METTL3, we retrieved the expression levels of healthy tissue and tumor tissue in different parts from the GTEx and GEPIA databases, respectively." (PMID 32211315, 2020). "Immunohistochemistry (IHC), western blots, and RT-qPCR were used to detect the expression of METTL3 in PC, and the results showed that METTL3 protein and mRNA levels were significantly higher in tumor samples than in paracancer samples." (PMID 32754191, 2020). "Next, we further investigated the function of METTL3 overexpression in RB tumorigenesis in the subcutaneous tumour model." (PMID 33090698, 2020). "Consistent with our previous in vitro results, knockout of METTL3 significantly abolished the inhibitory effects of sorafenib treatment in vivo, as indicated with the increased tumor size and tumor weight." (PMID 32368828, 2020). "The subcutaneous tumor xenograft model results indicated that knocking down METTL3 induced an obvious retardation of tumor growth, which was further corroborated by the reduced radiance value measured by the in vivo imaging system after 40 days." (PMID 33121495, 2020). "In nude mouse xenograft models, tumors induced by METTL3-overexpression cells showed significantly larger tumor volumes and heavier tumor weights than those in the control group." (PMID 32175271, 2020). "We further demonstrated that miR‐186 directly targeted METTL3 and ectopic overexpression of miR‐186 significantly inhibited aggressive tumour phenotypes of HB, both in vitro and in vivo." (PMID 31967701, 2020). "We analyzed mRNA levels of METTL3 in tumor tissues and normal liver tissues from two independent cohorts." (PMID 32068977, 2020). "A mechanistic study to support the role of METTL3 in the regulation of tumour-derived MDSC differentiation is currently underway, and the underlying mechanisms will be clarified in the near future." (PMID 33059689, 2020). "While METTL3 exhibits oncogenic functions in most cancer types, it was also reported as a tumor suppressor in some cases." (PMID 32854717, 2020). "Immunohistochemical staining was performed on 57 tumor tissues of ESCA patients who underwent PET/CT scan before surgery to evaluate the expression of METTL3, glucose transporter 1 (GLUT1), and hexokinase 2 (HK2) in tumor tissues and peritumoral tissues." (PMID 32626532, 2020). "It is of note that METTL3-mediated m6A methylation plays a role in promoting tumor progression in many cancers, thus it is worth exploring the role of DCA in other cancers." (PMID 32514152, 2020). "In this study, we demonstrated the tumour‐promoting function and specific regulatory mechanism of m6A axis, consisting of the core ‘writer’ protein METTL3 and the major reader protein YTHDF2." (PMID 32126149, 2020). "The high levels of METTL3 and CD33+ MDSCs in the CC tumour microenvironment were significantly associated with poor disease-free survival (DFS) and overall survival (OS) in CC patients." (PMID 33059689, 2020). "The tumor-promoting effect of METTL3 was also reflected by its activity to mediate YTHDF2-dependent mRNA decay of SOCS2, a suppressor of cancer metastasis." (PMID 33584787, 2020).
tumor (continued). "To decipher the mechanisms of METTL3 in tumor growth and metastasis, we performed correlation analysis between METTL3 mRNA and all the other mRNA, miRNA, and long ncRNA in the TCGA-STAD database." (PMID 33037176, 2020). "Phosphorylated AKT was consequently confirmed as the downstream of METTL3/YTHDF2/LHPP/NKX3–1 to induce tumor proliferation and migration." (PMID 33121495, 2020). "The mice bearing DLBCL cells with silenced expression of METTL3 displayed remarkably lower luminescence intensities than those in the control group, suggesting a METTL3 knockdown-induced inhibition in the tumor progression in vivo." (PMID 33061938, 2020). "To assess the potential function of cyclin E1 in the tumour‐promoting functions of METTL3 in CRC, we transfected CCNE1 plasmids into HT29 and LoVo cells." (PMID 32039568, 2020). "Suppressor of cytokine signaling 2 (SOCS2), a direct downstream target of METTL3, inhibited tumor progression." (PMID 32733807, 2020). "Ectopic expression of HK2 or SLC2A1 partially restored the proliferation and colony formation ability of METTL3-knockout cells and tumor growth." (PMID 32245489, 2020). "In non-tumor cells, METTL3 methylated primary miRNAs, such as pri-let-7e and pri-miR221, and facilitated their maturation." (PMID 33037176, 2020). "IHC showed that Mettl3 depletion led to a lower level of PDK4 in xenograft tumor tissues, which suggested that deletion of Mettl3 can regulate the expression of PDK4 in vivo." (PMID 32444598, 2020). "In anti‐tumor therapy perspective, targeting METTL3 is of particularly promise when combined with other antimetabolites." (PMID 32068977, 2020). "In cultured CRC cells and xenograft mouse models, downregulation of METTL3 markedly suppresses tumor growth and inhibits glycolysis progression in CRC." (PMID 32245489, 2020). "Silencing METTL3 expression in GBM can significantly inhibit tumour growth and prolong mouse survival time, which is consistent with clinical observations that an increase in METTL3 expression is consistent with the poor survival of patients with GBM." (PMID 32943100, 2020). "As expected, in rescue experiments, silencing SETD7 or KLF4 abrogated the tumour‐suppressive phenotypes by depletion of METTL3." (PMID 32126149, 2020). "The colony formation assay also revealed that down‐regulated METTL3 reduced the colony‐forming capacity of tumour cells." (PMID 33090698, 2020). "Accordingly, a high level of METTL3 in tumour-infiltrating immune cells was negatively correlated with DFS (P = 0.002) and OS (P < 0.001) in CC patients." (PMID 33059689, 2020). "We identified that the level of METTL3 was significantly increased in HCC tissues compared with the corresponding para‐tumor normal liver tissues (P < .0001)." (PMID 32068977, 2020). "HBXIP upregulates the expression of METTL3 via inhibiting the function of the tumor suppressor miRNA let-7 g, forming a positive feedback loop of METTL3/HBXIP/let-7 g/METTL3." (PMID 32513173, 2020). "The number of CD33+ cells was positively correlated with the expression of METTL3 in tumour cells (R = 0.145, P = 0.041) and tumour-infiltrating immune cells (R = 0.182, P = 0.011)." (PMID 33059689, 2020). "In our study, we found that microvessel density was significantly higher in tumor tissues with high METTL3 expression than in those with low expression." (PMID 32429972, 2020). "To study the function of METTL3 in the regulation of RB, we first analysed the expression of METTL3 in RB patients and found that METTL3 is expressed in RB tumour samples." (PMID 33090698, 2020). "TCGA database search revealed that PEDF was overexpressed in DLBCL tissues, and further linear regression analysis identified a positive correlation between increased expression of PEDF and METTL3 expression in DLBCL tumor tissues and whole blood." (PMID 33061938, 2020).
tumor (continued). "The results of immunohistochemistry showed that METTL3 expressed in tumor tissue with high positive rate is expected to become a new pathological diagnosis index and a potential therapeutic target." (PMID 32626532, 2020). "In that study, overexpression of METTL3 promoted tumor growth in CRISPR/dCas9-VP64 models in vivo and in vitro, indicating its positive correlation with HCC." (PMID 32733807, 2020). "Li and collaborators demonstrated that METTL3 was a potential prognostic marker of RCC, and the expression levels of METTL3 are interrelated to tumor size and histological grade." (PMID 33015074, 2020). "For instance, in CRC, METTL3 can promote tumor progression through enhancing the expression of either MYC or CCNE1." (PMID 33015074, 2020). "The high level of METTL3 in tumour cells was significantly correlated with decreased DFS (P < 0.001) and OS (P < 0.001) in CC patients." (PMID 33059689, 2020). "Further more, we confirmed decreased expression of CTNNB1 downstream transcription factor TCF4 and target gene Cyclin D1 in METTL3 knockout HB cell Huh6 and tumor-bearing tissues of mice." (PMID 31870368, 2019). "Depletion of METTL3 results in a decrease in cell proliferation, colony formation, and migration in vitro and inhibits tumor cell proliferation and metastasis in vivo." (PMID 31801551, 2019). "METTL3, acting as the key component of N6-methyltransferase complex, has been reported to play an important role in many tumor types." (PMID 31230592, 2019). "a, Subcutaneous tumor models in nude mice showing the tumor size at day 28 after the implantation of METTL3-knockdown and control SW620 and HCT116 cells (n = 5 mice per group)." (PMID 31230592, 2019). "Our analysis in both protein (MS) and mRNA (TCGA) datasets suggested that writers and readers were tumor suppressive while erasers play a tumorigenic role in GC, however, controversial roles of METTL3/YTHDF2 in other cancer types were reported." (PMID 31243897, 2019). "b, Representative and quantification of H&E and immunostaining (scale bar: 100 μm) of METTL3, SOX2, and EpCAM in subcutaneous tumor models of METTL3 knockdown and control SW620 and HCT116 cells." (PMID 31230592, 2019). "The data described in this review suggest that METTL3 is upregulated in most cancer tissues and cell lines and plays an oncogenic role in tumor formation and progression." (PMID 31921660, 2019). "Accordingly, METTL3 affects the tumor formation by the regulation the m6A modification in the mRNAs of critical oncogenes or tumor suppressors." (PMID 31228940, 2019). "The tumor growth rate was slower, and the xenograft tumor weight was reduced, when METTL3-knockdown SW620 and HCT116 cells were implanted, compared with the control cells." (PMID 31230592, 2019). "Through m6A modification, METTL3 modulates tumor cell proliferation, invasion, migration, tumor formation, and drug resistance." (PMID 31921660, 2019). "Applying driverMAPS to TCGA data of 20 tumor types, we identified 159 new potential driver genes, including the mRNA methyltransferase METTL3-METTL14." (PMID 31363082, 2019). "In cutaneous squamous cell carcinoma (cSCC), up-regulated METTL3 promotes △Np63 expression, thereby enhancing cSCC cell proliferation and tumor growth." (PMID 31801551, 2019). "Next, we studied the role of METTL3-m6A-CDCP1 axis in regulation of in vivo tumorigenesis using xenograft tumor models." (PMID 30796352, 2019). "Our results uncover a significant oncogenic role for METTL3 in tumor progression, though there are other studies that had suggested some controversial conclusions." (PMID 31230592, 2019). "RNA N6-methyladenosine (m6A) is an emerging regulatory mechanism for gene expression and methyltransferase-like 3 (METTL3) participates in tumor progression in several cancer types." (PMID 31230592, 2019). "Then, downregulating METTL3 expression inhibited tumor cell growth and invasion and promoted cell apoptosis." (PMID 31757221, 2019).
tumor (continued). "The present study demonstrates that the METTL3/miR-1246/SPRED2 axis plays an important role in tumor metastasis and provides a new m6A modification pattern in CRC development." (PMID 31492150, 2019). "Considering that SOX2 is considered the important CSC marker to promote tumor initiation and participate in tumor metastasis, we presumed that METTL3 promoted CRC stemness and metastasis in an m6A-dependent manner to maintain SOX2 expression." (PMID 31230592, 2019). "The correlation analysis revealed a positive correlation between the expression of METTL3 and miR221 (r = 0.2928, P < 0.01) or miR222 (r = 0.2386, P < 0.01) in 56 tumor tissues." (PMID 31228940, 2019). "Other mechanisms by which METTL3 promotes tumor metastasis need to be urgently investigated because of its pivotal role in regulating synthesis of other RNAs, including mRNA and other noncoding RNAs." (PMID 31492150, 2019). "Collectively, the research on METTL3 and SOX2 suggests that METTL3-mediated m6A modification regulates SOX2-associated stem cell self-renewal and tumor progression." (PMID 31921660, 2019). "In this tumor model, METTL3-mediated m6A modification targets suppressor of cytokine signaling 2 (SOCS2), promoting its degradation, in a process dependent of YTHDF2 reader." (PMID 30428628, 2018). "As an important “writers”, several studies have indicated the tumour suppressor role of METTL3 with up‐regulating m6A modification." (PMID 30039919, 2018). "METTL3 knockdown also decreases cell cycle arrest in G1 phase and P21 expression, which acts as a suppressor in tumor." (PMID 30062093, 2018). "Compared to mice receiving control-shRNA-transduced GSCs (control GSCs), mice grafted with METTL3 KD GSCs exhibited much bigger tumors, as revealed by a substantial increase in tumor bioluminescence intensity." (PMID 28297667, 2017). "The results indicated that expression of METTL3 was significantly lower in RCC samples compared with adjacent non-tumor samples (P<0.05)." (PMID 29221190, 2017). "However, cells pretreated with 1,3-diCQA prior to inoculation counteracted the tumor-suppressive effects of METTL3 silencing." (PMID 42064710, 2026). "Targeting METTL3 increases the accumulation of dsRNAs derived from both pre-existing and newly transcribed REs, amplifying immunostimulatory signalling and activating cell-intrinsic anti-tumour immunity." (PMID 42135281, 2026). "In addition, there is a clinical trial (NCT06762925) targeting METTL3 peptide inhibitors for urinary tract tumors, which aims to reshape the tumor microenvironment and enhance the anti-tumor immune response." (PMID 41362736, 2026). "Additionally, ubiquitination at sites such as K480 and K459 has been reported to target METTL3 for proteasomal degradation in tumor cells." (PMID 41457744, 2026). "During this process, Mettl3 interacts with the DiGeorge syndrome critical region 8 protein and positively modulates the pri-miR-320b maturation process in an m6A-dependent manner, thereby promoting tumor growth." (PMID 41517663, 2026). "Some METTL3 inhibitor have also been proven to exhibit the good anti-tumor activity." (PMID 41362736, 2026). "Additionally, tumor-derived exosomal microRNA-4443 (miR-4443) indirectly upregulates this expression by downregulating METTL3, thus decreasing m6A modification on FSP1 mRNA." (PMID 40862825, 2025). "Next, we investigated the impact of METTL3 on tumor proliferation in vitro and in vivo." (PMID 39472692, 2025). "STM2457, a selective METTL3 inhibitor, has shown anti-tumor effects in many cancers including OSCC." (PMID 40338154, 2025). "Therefore, developing targeted therapeutic drugs against key proteins such as YTHDC1 and METTL3, based on the regulatory mechanisms of m6A modification, holds promise for enhancing the anti-tumor functions of B cells." (PMID 39987091, 2025). "METTL3 expression is enhanced by pathways commonly dysregulated in this tumor, such as PDGF-EGR1." (PMID 40002173, 2025).